FGFR4 (fibroblast growth factor receptor 4)
Diseases named in the same sentence as FGFR4 in open-access papers (continued):
Sharing a sentence is not in itself a finding about the gene and the disease.
cutaneous melanoma (3 papers, 2009 to 2023). A primary melanoma arising from atypical melanocytes in the skin. "Overexpression of the FGFR4 protein has been associated with cutaneous melanoma progression." (PMID 19500394, 2009). "Overexpression of the FGFR4 protein has been linked to cutaneous melanoma progression." (PMID 19500394, 2009). "Further, through the GEPIA database, in cutaneous melanoma, we examined the association between the ERBBs and 31 genes were close to each other and frequently altered and observed that all the genes except KIT, ALK, NTRK1, FGFR4, and MET were affected by the changes of some ERBB family members." (PMID 33732282, 2021).
embryonal rhabdomyosarcoma (3 papers, 2013 to 2025). A poorly circumscribed morphologic variant of rhabdomyosarcoma. "Although this models human embryonal rhabdomyosarcoma most closely, expressing human wild-type FGFR4 in a mouse cell or growing in an environment with murine stromal growth factors may alter its behavior differently." (PMID 24124571, 2013).
Ewing sarcoma (3 papers, 2023 to 2025). A small round cell tumor that lacks morphologic, immunohistochemical, and electron microscopic evidence of neuroectodermal differentiation. "This included FGFR1 amplification in RMS (n = 3), Ewing sarcoma (ES; n = 2), OS (n = 1) and a sarcoma other (n = 1); FGFR3 amplification in a CNS tumour (n = 1); and FGFR4 amplification in RMS (n = 3)." (PMID 37130917, 2023).
invasive ductal carcinoma (3 papers, 2016 to 2022). "FGFR4 is overexpressed in 8/8 ILC cell line models and 4/4 invasive ductal carcinoma (IDC) cell line models at the RNA level relative to parental cells subjected to short-term estrogen deprivation." (PMID 31263748, 2019). "Here, we show that FGFR4 expression also increases dramatically in endocrine-treated distant metastases, with an average fold change of 4.8 relative to the paired primary breast tumor for ILC, and 2.4-fold for invasive ductal carcinoma (IDC)." (PMID 31263748, 2019).
metastatic colorectal cancer (3 papers, 2013 to 2024). "At the pathway level, we detected that the alteration rate (mutation and copy number variation) of the genes involved in MAPK signaling pathways, including FGFR1, FGFR2, FGFR3, FGFR4, BRAF, and MEK, was significantly lower in metastatic colorectal cancer tissue compared to the primary site." (PMID 29038591, 2017).
myocardial infarction (3 papers, 2019 to 2025). Gross necrosis of the myocardium, as a result of interruption of the blood supply to the area, as in coronary thrombosis. "Recently, FGF23 has been found to promote fibrosis in injury-primed renal fibroblasts through activation of both TGFβ/Smad and FGFR4/PLCγ/calcineurin/NFAT signaling, and to cause cardiac fibrosis by upregulating β-catenin and TGFβ in vitro and after myocardial infarction in vivo." (PMID 31540546, 2019).
nasopharyngeal carcinoma (3 papers, 2017 to 2021). A carcinoma arising from the nasopharyngeal epithelium. "FGFR4 expression was elevated in nasopharyngeal carcinoma tissues, and FGFR4 knockdown reduced proliferation and migration of nasopharyngeal carcinoma cells." (PMID 33801580, 2021). "After treatment with MSC-exosomes, phosphorylated FGFR4 and ERK in nasopharyngeal carcinoma (NPC) cells increased, and the expression of EMT markers changed, presenting as down-regulation of E-cadherin, up-regulation of N-cadherin, and vimentin." (PMID 31357383, 2019).
nonalcoholic steatohepatitis (3 papers, 2021 to 2022). "The authors held that fibroblast growth factor 19 - fibroblast growth factor receptor 4 (FGF19-FGFR4) pathway, which was target of lenvatinib, were involved in the tumorigenesis of non-alcoholic steatohepatitis- and alcohol-associated HCC and consequently, these HCCs responded better to lenvatinib." (PMID 36483039, 2022).
pancreatic ductal adenocarcinoma (3 papers, 2020 to 2025). An infiltrating adenocarcinoma that arises from the epithelial cells of the pancreas. "Research on pancreatic ductal adenocarcinoma cells demonstrated effectiveness of a selective fibroblast growth factor receptor 4 (FGFR4) inhibitor—BLU9931—in the induction of senescence." (PMID 36232388, 2022). "In this study, we examined the expression and roles of FGF19/FGFR4 signaling in human pancreatic ductal adenocarcinoma (PDAC)." (PMID 33066597, 2020).
rectal cancer (3 papers, 2016 to 2024). A primary or metastatic malignant neoplasm that affects the rectum. "The results of our association analysis of the clinicopathologic variables of the CRC patients who carried FGFR4 variants showed that being a carrier of the rs1966265 GA genotype was associated with rectal cancer and advanced-stage (stage III) disease." (PMID 38540215, 2024). "In conclusion, our results demonstrate an association of FGFR4 SNPs (rs1966265 and rs351855) with the metastatic potential in rectal cancer." (PMID 34071523, 2021). "Using the GEPIA tool, we compared the FGFR4 expression levels in colon and rectal cancer tissue samples with those in normal tissue samples." (PMID 38540215, 2024). "Our data revealed an influence of FGFR4 gene variations on the metastasis of rectal cancer; however, additional work is needed to address several limitations in the study." (PMID 34071523, 2021). "The results demonstrate that high FGFR4 expression in the tumor correlated with poor response to radiotherapy in 43 patients who underwent neoadjuvant treatment for rectal cancer." (PMID 27650548, 2016).
retinoblastoma (3 papers, 2019 to 2024). A malignant tumor that originates in the nuclear layer of the retina. "It was found that 3 (6.1 percent) patients had a history of first-degree-associated retinoblastoma when evaluating the association of the FGFR4 p.Gly388Arg variant with family history." (PMID 33456465, 2020). "Nonetheless, our statistical study clearly showed that, in advanced stage patients diagnosed with retinoblastoma prior to 24 months, the FGFR4 p.Gly388Arg allele was significantly higher." (PMID 33456465, 2020). "The effect of the FGFR4 p.Gly388Arg variant on retinoblastoma pathogenesis has been investigated in this planned study." (PMID 33456465, 2020). "In this study, in patients with a family history of retinoblastoma, the FGFR4 p.Gly388Arg mutation rate was recognized as “almost significant” (e.g., p=0.08∗∗)." (PMID 33456465, 2020). "In patients with advanced retinoblastoma who were diagnosed with retinoblastoma prior to 24 months, the FGFR4 p.Gly388Arg allele was found to be significantly higher." (PMID 33456465, 2020). "This research indicates that the variant of FGFR4 p.Gly388Arg may have a population-specific polymorphism as a result of analysis performed in retinoblastoma patients and control groups after sequencing by the Sanger sequencing process." (PMID 33456465, 2020). "In this context, it can be thought that the variant of FGFR4 p.Gly388Arg in the FGFR4 gene, which is known to play a role in cancer progression and retinal development, may be a candidate mechanism and marker gene that triggers retinoblastoma formation." (PMID 33456465, 2020). "Using the Sanger sequencing methods, the FGFR4 p.Gly388Arg variant was bidirectionally sequenced in 49 patients with non-RB1 gene mutation in retinoblastoma patients and 13 healthy first-degree relatives and 146 individuals matched by sex and age in the control group." (PMID 33456465, 2020). "A candidate mechanism and marker gene that activates the formation of retinoblastoma in this context may be considered to be the FGFR4 p.Gly388Arg variant in the FGFR4 gene, which is known to be involved in the development of cancer and retinal growth." (PMID 33456465, 2020). "Our first goal in this study was to establish if the variant FGFR4 p.Gly388Arg may be another primary mechanism in the formation of retinoblastoma other than the RB1 gene." (PMID 33456465, 2020). "Furthermore, taking into account the status of the FGFR4 p.Gly388Arg allele, this polymporphism can be considered to be a novel alternative for predicting clinical development and assessing the stage of disease in patients with advanced stage retinoblastoma." (PMID 33456465, 2020). "The goal of this study was to investigate the FGFR4 p.Gly388Arg variant that plays role in the progression of cancer and retinal growth and may be an effective candidate variant in the Turkish population in retinoblastoma patients with no RB1 gene mutation." (PMID 33456465, 2020). "This is the first study suggesting that these genes, FGFR4, NQO1, ACADS CX3CR1, GBE1, KRT85, and TYR genes, may play a role in the etiology of Rb." (PMID 31207142, 2019).
skin cancer (3 papers, 2009 to 2024). "Given the power of this study, we did not detect any contribution of genetic variants in the FGFR2 or FGFR4 genes to inherited predisposition to skin cancer among Caucasian women." (PMID 19500394, 2009). "In conclusion, we did not detect any contribution of genetic variants in the FGFR2 or FGFR4 genes to inherited predisposition to skin cancer among Caucasian women." (PMID 19500394, 2009). "Neither mutations in FGFR4 nor in FGFR2 as a possible contribution to an inherited predisposition to skin cancer, could, however, be detected in healthy caucasian women." (PMID 22007305, 2011). "Genetic variants of FGFR4 and FGFR2 seem, therefore, to function as potential biomarkers for progression rather than as a risk factor of skin cancer development." (PMID 22007305, 2011).
thymoma (3 papers, 2008 to 2022). A neoplasm arising from the epithelial cells of the thymus. "Also in ATP binding, the fibroblast growth factor receptor FGFR4 showed over 4-fold decrease in two core probe-sets in MG-thymoma." (PMID 18545673, 2008). "Significant enrichment of mutated genes of the RAS and PI3K-Akt signalling pathways was reported in thymomas (AKT3, ALK, CSF1R, FGFR4, KRAS, NRAS, HRAS, PIK3CA), and their role in thymoma development was suggested." (PMID 35884448, 2022).
urothelial cell carcinoma (3 papers, 2019 to 2021). "FGFR4 rs2011077 TC+CC polymorphism is associated with higher tumor stage, tumor size, and grading in urothelial cell carcinoma." (PMID 33017009, 2020). "This study explored the effect of FGFR4 single-nucleotide polymorphisms (SNPs) on the clinicopathological characteristics of urothelial cell carcinoma (UCC)." (PMID 31878098, 2019).
acromegaly (2 papers, 2011 to 2021). Acromegaly is an acquired disorder related to excessive production of growth hormone (GH) and characterized by progressive somatic disfigurement (mainly involving the face and extremities) and systemic manifestations. "Additionally, whole genomic regions of seven genes (HMGA2, FGFR4, PTTG1, RB1, GNAS, AIP, GPR101) associated with acromegaly were added to the profiling target." (PMID 34400688, 2021).
adenoma (2 papers, 2015 to 2025). A neoplasm arising from the epithelium. "Adenomas with Ki-67 expression of ≥3% had higher FGFR4 expression levels than those with <3% expression (p = 0.002)." (PMID 40806692, 2025). "The protein from primary human adenomas migrated as a 65 kDa species, which corresponds to the predicted size of ptd-FGFR4." (PMID 40806692, 2025). "FGFR4 protein expression was frequently found in adenomas containing GH, ACTH, or FSH/LH and was also found in null cell adenomas, but reactivity was relatively rare in prolactin-containing adenomas in both Japanese and Canadian groups." (PMID 40806692, 2025). "They found that median H-scores for FGFR4 were higher in patients without remission, in those with residual lesions, and in T2-hyperintense adenomas (p < 0.05)." (PMID 40806692, 2025).
brain tumor (2 papers, 2025). "The rates of alterations of the FGFR1, FGFR2, FGFR3, and FGFR4 genes in brain tumor patient samples were 1%, 1.5%, 1.7%, and 0.9%, respectively, and pediatric brain tumors had among the highest levels of FGFR gene family alterations among all brain tumor databases." (PMID 40510032, 2025).
cholestasis (2 papers, 2023 to 2024). Impairment of the bile flow caused by obstruction within the liver, or outside the liver in the bile duct system. "Moreover, PM2.5 significantly increased the expression of core genes associated with the biosynthesis (Cyp7a1, Cyp27a1, Baat, and Bacs) and regulation (Shp, Fgfr4) of primary bile acids, suggesting that cholestasis is an important cause of PM2.5 hepatotoxicity." (PMID 39195689, 2024). "Compared with the control group, the hyperuricemia mice showed increased mRNA levels of hepatic FXR and FGFR4, as well as the ileal FXR and FGF15, which were different from those in cholestasis." (PMID 38034015, 2023).
colitis (2 papers, 2022 to 2025). Inflammation of the colon. "Previous studies have found that FGFR4 deficiency or inactivation in mouse BMDMs aggravated LPS-induced M1 polarization and inflammation, and myeloid-specific FGFR4 deletion exacerbated colitis in mice." (PMID 40825908, 2025).
colorectal neoplasm (2 papers, 2021 to 2026). A benign or malignant neoplasm that affects the colon or rectum. "In the present study, 413 CRC cases were recruited to explore the risk effect of FGFR4 gene polymorphisms on the development of colorectal neoplasm." (PMID 34071523, 2021). "FGFR4 was prioritized due to its overexpression in colorectal tumors." (PMID 41681889, 2026).
congenital heart disease (2 papers, 2018). A heart disease that is present at birth. "Exome sequencing of congenital heart disease (CHD) patients identified three individuals with damaging mutations in fibroblast growth factor receptor 4 (FGFR4)." (PMID 30564136, 2018). "However, interestingly, FGFR4 is not a shared gene between all four cases having heart defects." (PMID 29416564, 2018).
diabetic cardiomyopathy (2 papers, 2017 to 2022). Diabetic cardiomyopathy is a disorder of the heart muscle in people with diabetes. "Blockade of FGFR signaling using both a pan-FGFR small chemical inhibitor and a FGFR4-specific blocking antibody inhibited the concentric hypertrophy associated with diabetic cardiomyopathy in mice." (PMID 35513431, 2022).
emphysema (2 papers, 2020 to 2024). "As Fgfr4−/− lungs show airway inflammation and airway enlargement consistent with emphysema, we wanted to assess the effect of constitutive FGFR4 activation." (PMID 32793609, 2020). "Collectively, full Fgfr4−/− mice at 6 months of age showed evidence of airway inflammation and airway enlargement consistent with emphysema." (PMID 32793609, 2020). "Our results indicate that adult Fgfr4−/− mice demonstrate a lung phenotype consisting of widened airway spaces, increased airway inflammation, bronchial obstruction, and right ventricular hypertrophy consistent with emphysema." (PMID 32793609, 2020). "The Fgfr4-knockout mouse is not lethal, though we have shown that the adult mouse develops airway inflammation along with changes consistent with emphysema; the murine lung is not a great model to study airway biology, especially CF." (PMID 38916962, 2024).
endometriosis (2 papers, 2021 to 2023). The growth of functional endometrial tissue in anatomic sites outside the uterine body. "Here, we provide FGFR4, NALCN, and NAV2 as novel high-risk candidate genes for familial endometriosis." (PMID 37789421, 2023). "Segregating variants in FGFR4, NALCN, and NAV2 were screened in 92 individuals with endometriosis and in 19 individuals with both endometriosis and an associated tumor." (PMID 37789421, 2023). "While in silico predictions and the known protein function provide FGFR4 as a plausible candidate gene for endometriosis, additional studies are required to confirm whether this alteration is a real high-risk predisposing factor." (PMID 37789421, 2023). "High expressions of FB receptors associated with pro-fibrosis and adhesion, such as FGFR1, FGFR4, ICAM, and CD44, were activated by ligands in immune cells, suggesting that alternate endometriosis immune cells played an important role in promoting lesion development." (PMID 34233737, 2021).
hepatoblastoma (2 papers, 2024). Hepatoblastoma (HB) is a malignant hepatic tumor and is the most common pediatric liver cancer. "Thus, these FGF19-positive hepatoblastoma tumoroids depended on the endogenous expression of FGF19 and subsequent signaling through FGFR4 and MAPK." (PMID 39567523, 2024).
Hypercholesterolemia (2 papers, 2013 to 2023). An increased concentration of cholesterol in the blood. "Thus, silencing FGFR4 leading to activation of the intestinal FXR-FGF15/19 axis allows for advantageous effects of FGF15/19 while avoiding the risk of hypercholesterolemia and hepatic carcinogenesis." (PMID 36586437, 2023). "Interestingly, studies have shown that a whole body FGFR4 KO does not change or even increase hypercholesterolemia, despite stimulation of bile acid synthesis." (PMID 36586437, 2023).
hypophosphatemia (2 papers, 2013 to 2019). Lower than normal levels of phosphates in the circulating blood. "In a subsequent study, however, FGF23 did not reduce serum phosphorus levels in double Fgfr3/Fgfr4 KO mice, suggesting that FGFR3 and FGFR4 play redundant roles in phosphate regulation, and perhaps that FGFR1 activation is not sufficient for FGF23 to induce hypophosphatemia." (PMID 23451204, 2013).
intrahepatic cholangiocarcinoma (2 papers, 2017 to 2022). A carcinoma that arises from the intrahepatic bile duct epithelium in any site of the intrahepatic biliary tree. "We investigated the gene expression and clinical significance of FGFR4 and related pathways in intrahepatic cholangiocarcinoma (iCCA)." (PMID 28445152, 2017).
invasive lobular breast carcinoma (2 papers, 2021 to 2022). An infiltrating lobular adenocarcinoma of the breast. "For example, 3% of desmoplastic small round cell tumours have FGFR4 V550L mutations, and 3.5% of endocrine-treated metastatic invasive lobular breast carcinomas harbour FGFR4 mutations, including N535K/D and V550L/M." (PMID 36097178, 2022). "In addition, FGFR4 is implicated in metastasis and endocrine resistance in invasive lobular carcinoma, and a recent study indicates that FGFR4 promotes transition from a more differentiated, luminal phenotype to a highly proliferative and metastatic, HER2-enriched one." (PMID 34344433, 2021).
iron deficiency (2 papers, 2013 to 2022). "We found that on adenine, both Fgfr4+/+ and Fgfr4−/− mice show comparable macroscopic parameters and degrees of functional iron deficiency." (PMID 35302487, 2022).
liver disease (2 papers, 2016 to 2022). "As previously seen with both FGF19 and FGFR4, EpCAM expression also appeared to increase with the histological severity of inflammation and liver disease, demonstrating a significant positive correlation between EpCAM expression and histopathologic changes from ST to HCC (r = 0.947)." (PMID 27447573, 2016).
metastatic cancer (2 papers, 2019). A carcinoma which has spread from the original site of growth to another anatomic site. "Although the critical role of FGFR4 in metastasis has been demonstrated in animal models of several cancers, prospective studies are warranted to provide evidence regarding the therapeutic efficacy of FGFR4 inhibitors in clinical metastatic cancers." (PMID 30634399, 2019).
oral cancer (2 papers, 2017 to 2021). "Our results showed that FGF19/FGFR4 were involved in the melatonin modulated oral cancer migration and invasion." (PMID 34576070, 2021).